TRMT1 (tRNA methyltransferase 1)
Description:
Dimethylates a single guanine residue at position 26 of most nuclear- and mitochondrial-encoded tRNAs using S-adenosyl-L-methionine as donor of the methyl groups. tRNA guanine(26)-dimethylation is required for redox homeostasis and ensure proper cellular proliferation and oxidative stress survival.
Synonyms: hTRM1; FLJ20244; TRM1; MRT68
Tractability: Antibody: the Human Protein Atlas places it where antibodies can reach. PROTAC: ubiquitination databases record sites on it; its protein half-life has been measured.
Target class: Enzyme; Transferase
Gene: Protein-coding gene on chromosome 19 (13,104,899 to 13,117,567, reverse strand). Ensembl gene ENSG00000104907.
Subcellular location: Mitochondrion (Isoform 1); Nucleus (Isoform 3); Cytoplasm
Subcellular location (Human Protein Atlas): Cytosol; Plasma membrane; Nucleoplasm
Pathways (Reactome):
Metabolism of RNA: tRNA modification in the nucleus and cytosol
Gene Ontology:
Molecular function: protein binding; RNA binding; tRNA (guanine(26)-N2)-dimethyltransferase activity; catalytic activity, acting on a tRNA; metal ion binding; S-adenosylmethionine-dependent methyltransferase activity; tRNA (guanine) methyltransferase activity
Biological process: tRNA N2-guanine methylation; tRNA modification; tRNA processing
Cellular component: cytoplasm; mitochondrion; nucleus; nucleoplasm
Genetic constraint (gnomAD): Loss-of-function variants: 62 observed, 78.78 expected, observed/expected ratio (o/e) 0.79, 90% interval 0.64 to 0.97. The upper end of that interval is the gene's LOEUF score, 0.97, which puts it in group 4 of 6, group 1 being the genes least tolerant of losing a copy. Missense variants: 869 observed, 934.67 expected, observed/expected ratio (o/e) 0.93, 90% interval 0.88 to 0.98. Synonymous variants: 382 observed, 369.67 expected, observed/expected ratio (o/e) 1.03, 90% interval 0.95 to 1.12.
Gene-disease validity (ClinGen):
ClinGen rates the evidence that TRMT1 causes each of these diseases.
complex neurodevelopmental disorder (autosomal recessive): Definitive. A disorder that involves more than one phenotype associated with the central nervous system, including but not limited to intellectual disability, autism, and seizures (epilepsy).
Homologues: Orthologues: chimpanzee TRMT1 (99% identical), macaque TRMT1 (92% identical), pig TRMT1 (90% identical), dog TRMT1 (87% identical), mouse Trmt1 (83% identical), rat Trmt1 (83% identical), guinea pig TRMT1 (82% identical), rabbit TRMT1 (75% identical), tropical clawed frog trmt1 (60% identical), zebrafish trmt1 (58% identical), Drosophila melanogaster Trm1 (40% identical), Caenorhabditis elegans trm-1 (32% identical). Paralogues in human: TRMT1L (17% identical).
Diseases named in the same sentence as TRMT1 in open-access papers:
TRMT1 is named in the same sentence as 25 diseases in open-access papers, as found by Europe PMC text mining. Sharing a sentence is not in itself a finding about the gene and the disease. The quoted sentences say what the papers report.
Intellectual disability (7 papers, 2015 to 2025). "Altogether, these findings demonstrate that loss of TRMT1-catalyzed tRNA modifications leads to intellectual disability and provides insight into the molecular underpinnings of tRNA-modification deficiency caused by pathogenic TRMT1 variants." (PMID 40245862, 2025). "Other tRNA modification enzymes that are linked to intellectual disability include the tRNA methyltransferase TRMT1 and NSUN2, thiouridylase CTU2 and the adenosine deaminase ADAT3." (PMID 39723662, 2025). "Our studies define a core set of phenotypic features universally associated with pathogenic TRMT1 variants that encompasses global developmental delay, intellectual disability, and facial dysmorphism." (PMID 40245862, 2025). "Missense mutations in TRMT1 perturbs its tRNA modification activity and causes a deficiency in m22G formation, resulting in developmental delay, intellectual disability, and epilepsy." (PMID 39723662, 2025). "Altogether, these findings uncover the molecular effects of intellectual disability-associated TRMT1 variants on methyltransferase activity and tRNA binding that underlie deficits in m2,2G modification in human cells." (PMID 40245862, 2025). "This was followed by the identification of a single homozygous missense variant in TRMT1 associated with developmental delay, intellectual disability, and epilepsy." (PMID 40245862, 2025). "The 43 affected individuals with bi-allelic TRMT1 variants exhibited a core set of phenotypic features encompassing developmental delays, intellectual disability, and facial dysmorphism." (PMID 40245862, 2025). "Here, we describe 43 affected individuals from 31 unrelated families presenting with clinical features of intellectual disability in which exome or genome sequencing identified ultra-rare bi-allelic segregating TRMT1 variants." (PMID 40245862, 2025). "We identify bi-allelic variants in TRMT1, encoding a tRNA-modification enzyme, that cause intellectual disability and developmental delay." (PMID 40245862, 2025). "To examine the impact of intellectual disability-associated TRMT1 variants, we next investigated TRMT1 protein accumulation in available cell lines using immunoblotting." (PMID 40245862, 2025). "Several RNA methyltransferases have been linked to intellectual disability, such as the FtsJ RNA 2’-O-Methyltransferase 1 (FTSJ1), the TRNA Methyltransferase 1 (TRMT1) and NSUN2." (PMID 37612540, 2023). "Defects in the mitochondrial and nuclear writer of dimethylguanosine (m2,2G), tRNA methyltransferase 1 (TRMT1), have been shown to promote intellectual disabilities, with this epitranscriptomic system linked to redox metabolism." (PMID 30934574, 2019). "Expression of TRMT1 variants found in intellectual disability patients in TRMT1 knockout cells is not sufficient to catalyze the m2,2G modification at G26, whereas transfection of wildtype TRMT1 is able to recover tRNA G26 modifications." (PMID 30477220, 2018).
cognitive delay (2 papers, 2025). "Variants in TRMT1 are associated with SNHL, epilepsy, and cognitive delay, and highlight how defects in seemingly ubiquitous RNA modifications can result in selective vulnerability of cochlear and brain neurons." (PMID 41191133, 2025).
COVID-19 (2 papers, 2024 to 2025). A disease caused by infection with severe acute respiratory syndrome coronavirus 2. "Consistent with our results, a subset of proteomic studies has found decreased TRMT1 protein levels in SARS-CoV-2-infected human cells as well as in post-mortem tissue samples from deceased COVID-19 patients." (PMID 38814682, 2024). "Furthermore, it is possible that proteolysis of TRMT1 during SARS-CoV-2 infection could contribute to some cellular pathogenesis observed with COVID-19." (PMID 39773525, 2025).
viral infection (2 papers, 2020 to 2025). "Here, we summarize the latest findings concerning the roles of m5C RNA methyltransferases, namely, NOL1/NOP2/SUN domain (NSUN) proteins and DNA methyltransferase 2/tRNA methyltransferase 1 (DNMT2/TRDMT1) during viral infections." (PMID 33142933, 2020). "SARS-CoV-2 employs multiple mechanisms to disrupt host protein synthesis, and Mpro-mediated cleavage of human TRMT1 could contribute to the modulation of cellular translation during viral infection." (PMID 39773525, 2025). "Together, our studies corroborate and characterize cleavage of human TRMT1 by SARS-CoV-2 Mpro from the cellular to the atomic level and raise important new questions about the roles of tRNA methylation during viral infection." (PMID 39773525, 2025).
autosomal-recessive intellectual disability (1 paper, 2021). "TRMT1 has been considered as the cause of autosomal-recessive intellectual disability, but its role in cancers has not yet been reported." (PMID 35141213, 2021).
Burkitt lymphoma (1 paper, 2021). A rare form of malignant mature B-cell non-Hodgkin lymphoma. "For Family 3 (Burkitt’s lymphoma), TNNT3, SIRPB1, TRMT1, ITGB4, and DCHS1 were the top-five ranked genes." (PMID 34624066, 2021).
clear cell renal cell carcinoma (1 paper, 2022). "TRMT1 was found to serve as a promising biomarker in clear cell renal cell carcinoma." (PMID 36531021, 2022).
cognitive disorder (1 paper, 2025). A disease affects cognitive processes. "Moreover, the sparse number of TRMT1 variants that have been identified and characterized has limited our understanding of cognitive disorders associated with TRMT1 and their physiological consequences." (PMID 40245862, 2025).
HCMV infection (1 paper, 2015). "Although the TRMT1 KD did not significantly affect viral titers we observed a reproducible reduction in pp28 expression suggesting that the TRMT1 dimethylation activity might be playing a subtler role during HCMV infection." (PMID 26599541, 2015).
cancer (3 papers, 2018 to 2024). A tumor composed of atypical neoplastic, often pleomorphic cells that invade other tissues. "In addition, we identified several novel oncogenic enzymes with up-regulation in multiple cancer types, including PUS1, a tRNA pseudoridylate synthase, and TRMT1 and TRMT6, the tRNA methyltransferases." (PMID 30588513, 2018).
infection (3 papers, 2022 to 2025). The state of being infected such as from the introduction of a foreign agent such as serum, vaccine, antigenic substance or organism. "Future experiments in different virally infected cell types will be required to definitively establish how Mpro-directed TRMT1 cleavage impacts cellular and viral translation, viral infectivity and propagation, and oxidative stress phenotypes during infection." (PMID 39773525, 2025). "(A) Immunoblot of lysates prepared from 293T control-wild-type (WT) or TRMT1-knockout (KO) cell lines that were mock-infected (multiplicity of infection, MOI of 0) or infected with SARS-CoV-2 at MOI of 0.2 or 0.4 for 24 hr." (PMID 38814682, 2024). "In multiple independent replicates, MRC-5 cells infected with SARS-CoV-2 exhibited a ~30% reduction in TRMT1 levels at 24- and 48 hr post-infection compared to mock-infected cells." (PMID 38814682, 2024). "The virus multiplied less in cells that were unable to produce TRMT1 compared to normal human cells, suggesting that the virus benefits from TRMT1 early during infection, before inactivating it at a later point." (PMID 38814682, 2024). "(E, F) SARS-CoV-2 RNA copy number in control-WT or TRMT1-KO human 293T cell lines after infection at the indicated MOI for 24 hr." (PMID 38814682, 2024). "We also compared the levels of endogenous TRMT1 after infection with SARS-CoV-2 at a higher MOI of 5.0." (PMID 38814682, 2024). "SARS-CoV-2 Mpro-directed cleavage of TRMT1, and subsequent downregulation of tRNA m2,2G26 modification during infection, could therefore have direct impacts on both host and viral protein synthesis, as well as phenotypes linked to redox stress." (PMID 39773525, 2025). "Thus, the widespread changes in RNA modifications after infection with SARS-CoV-2 suggest that coronavirus infection could alter the levels or activity of multiple RNA modification enzymes in addition to TRMT1." (PMID 38814682, 2024).
tumor (2 papers, 2017 to 2026). "For the enhancer in chromosome 19, the target genes are TRMT1, TNPO2, NFIX, DNASE2, PRDX2, NANOS3, and LYL1, which was detected in 22 unique tumor samples." (PMID 29207666, 2017).
neurodevelopmental disorder (1 paper, 2025). A behavioral and cognitive disorder with onset during the developmental period that involves impaired or aberrant development of intellectual, motor, or social functions. "Using the GeneMatcher platform and data sharing with collaborators, we identified 31 unique families containing 43 individuals affected with neurodevelopmental disorders secondary to bi-allelic variants in TRMT1." (PMID 40245862, 2025).
TRMT1 also shares sentences with these, for which no sentence is quoted: autism spectrum disorder (1 paper); colon cancer (1); deafness (1); diabetes (1); epilepsy (1); glaucoma (1); glioma (1); leukodystrophy (1); melanoma (1); psoriasis (1); Tremor (1); vitiligo (1).